CTSD (cathepsin D)
Diseases named in the same sentence as CTSD in open-access papers (continued):
Sharing a sentence is not in itself a finding about the gene and the disease.
breast carcinoma (continued). "In line, mice xenografted with breast cancer cells that were overexpressed in CTSD demonstrated an increase in the number of tumor micro-vessels compared to mice that were xenografted with cells with normal CTSD expression." (PMID 36289617, 2022). "CTSD overexpression in breast cancer (MCF-7 and MDA-MB-231) cells promoted migration and invasion, and in addition, it reduced the protein levels of epithelial markers, such as E-cadherin." (PMID 36289617, 2022). "Over the past two decades, research has shown that overexpression and hypersecretion of CTSD have increased in many types of cancer, including ovarian cancer and breast cancer, endometrial cancer, lung cancer, and cancer glioma, melanoma, and prostate cancer." (PMID 34873574, 2021). "Increased expression and secretion of cathepsin D was observed in several cancers, including malignant melanoma, prostate, ovarian and breast cancer." (PMID 33802262, 2021). "In hormone-responsive breast cancer cells, transcription of CTSD is also induced by estradiol but blocked by TAM." (PMID 33861751, 2021). "Several biological factors are associated with breast cancer prognosis, such as the urokinase plasminogen activator (uPA), plasminogen activator inhibitor (PAI-1) and cathepsin D (Cath-D), and were omitted, as the data were unavailable in our settings." (PMID 33805407, 2021). "Estradiol-mediated enhanced secretion of pro-cathepsin D in breast cancer cells was also established." (PMID 34198733, 2021). "Cathepsin D is secreted in estrogen-dependent and estrogen-independent types of breast cancer, and for this reason, represents a significant prognostic marker." (PMID 34198733, 2021). "Human tissues used for positive controls demonstrated the expected staining patterns for cathepsin B on placenta, cathepsin D on breast carcinoma, cathepsin G on tonsil." (PMID 34621666, 2021). "Positive staining was demonstrated on human tissues: placenta for cathepsin B, breast carcinoma for cathepsin D and tonsil for cathepsin G." (PMID 34409065, 2021). "Collectively, this study represented a modality to explore novel relationships in a proteome complex and highlighted the functional roles of cathepsin D in treatment options for different subtypes of breast cancer." (PMID 32846884, 2020). "The results showed that cyanidin 3-[2-(glucosyl)-6-(sinapoyl)glucoside]-5-glucoside was successfully docked into the breast cancer-related proteins, CTSD and CA9." (PMID 32420359, 2020). "The lethal phenotype of constitutive CTSD knockout mice precluded in vivo tumor studies, thus hindering addressing the long-suspected role of CTSD in breast cancer by means of this approach." (PMID 33046706, 2020). "The novelty of our study is the investigation of cell type-specific functions of CTSD in vivo in a relevant primary breast cancer model." (PMID 33046706, 2020). "Depletion of CTSD gene expression by RNA interference decreases proliferative response and invasive potential in human breast cancer cell through suppressing the activation of EKR1/2 pathway." (PMID 32244796, 2020). "Since then, many investigations aimed to link CTSD protein levels or activities to the clinical outcome of breast cancer patients." (PMID 33046706, 2020). "Antibody against the aspartic protease cathepsin D (high production and secretion by breast cancer cells)." (PMID 32153582, 2020). "The most comprehensive study investigated tumor samples from 2810 breast cancer patients and uncovered a positive correlation of high CTSD protein levels in tumor homogenates with cancer relapse and patient death." (PMID 33046706, 2020). "The aspartic protease CTSD, a marker of a poor prognosis in breast cancer, is overproduced and hypersecreted by human breast cancer cells." (PMID 33177647, 2020). "CTSD overexpression promotes breast cancer cell migration, invasion, and metastasis by upregulating the expression of intercellular cell adhesion molecule-1." (PMID 32244796, 2020).
breast carcinoma (continued). "We set out to study cell type-specific functions of CTSD in breast cancer aided by transgenic PyMT mice." (PMID 33046706, 2020). "Gelsolin, Protein Daple, Heat shock protein HSP 90-beta, Alpha-1-antitrypsin, and Cathepsin D constitute serum biomarker signature for diagnosing early grade breast cancer." (PMID 31945087, 2020). "Together, these assays recapitulate the growth disadvantage of CTSD-deficient tumor cells seen in the primary MMTV-cre;Ctsd−/− PyMT breast cancer model and provide evidence for tumor cell-autonomous functions of CTSD." (PMID 33046706, 2020). "Cathepsin D (Cath-D) is overproduced and hypersecreted by breast cancer (BC) cells and is a poor prognostic marker." (PMID 32429078, 2020). "In this field, we were interested in the vectorization of pepstatin A, a peptide which does not cross cell membranes, but which is a potent inhibitor of cathepsin D, an aspartic protease particularly overexpressed in breast cancer." (PMID 30658511, 2019). "The aspartic protease cathepsin D (cath-D), a marker of poor prognosis in breast cancer (BC), is overproduced and hypersecreted by human BC cells." (PMID 30717773, 2019). "Cathepsin D is known to be overexpressed in breast cancer cells, where it promotes growth and metastatic activity." (PMID 31248089, 2019). "In vitro, ubiquitination and proteasomal degradation of hepsin occurred in response to cathepsin D expression in breast cancer cells, which led to increased metastasis in an in vivo model." (PMID 31399560, 2019). "Although the grafted tumor cells were not identified clearly on the bone surface, the strong expression of breast cancer markers cathepsin D and MMP1 near the bone surface indicate the successful tumorigenesis induced by cocultivation with tumor cells." (PMID 30400633, 2018). "In humans, proteins containing aspartyl protease domains includes the gene encoding Cathepsin D (CTSD), which has been implicated in breast cancer, and the gene encoding Cathepsin E (CTSE), which has been implicated in stomach cancer." (PMID 30118526, 2018). "Cathepsin D (CatD) is a soluble aspartic protease that is overexpressed and secreted in high amounts by breast cancer cells." (PMID 30086159, 2018). "The elevated expression of the lysosomal enzyme cathepsin D has been already correlated with breast cancer progression, opening the way to the design of cathepsin D inhibitors as potential anti-tumor agents." (PMID 30482226, 2018). "Positive controls for cathepsin B (brown), cathepsin D (brown) and cathepsin G (brown) demonstrated the expected staining patterns in human placenta, breast carcinoma and mouse bone marrow, respectively." (PMID 30177970, 2018). "Proteomic studies have recently confirmed the upregulation of CTSD in many types of cancer such as nasopharyngeal carcinoma, breast cancer, and colorectal cancer." (PMID 28423550, 2017). "In various human cancers, especially breast cancer, high levels of CTSD expression were also reported." (PMID 26056562, 2015). "In breast cancer, this protease is an independent marker of poor prognosis, shows an up-regulation of CTSD mRNA and represents a tissue marker with an increased risk of metastasis." (PMID 26203049, 2015). "The lysosomal protease cathepsin D (Cath-D) is overproduced in breast cancer cells (BCC) and supports tumor growth and metastasis formation." (PMID 26183398, 2015). "Both of them involved genes that encode membrane proteins, and siRNA knockdown of CTSD-IFITM10 fusion was associated with a decrease in live cells, suggesting that this fusion plays a role in breast cancer cell proliferation." (PMID 26561834, 2015). "ELISA was performed to confirm the altered expression levels of PRDX2, PRDX6, CTSB and CTSD in the serum among the breast cancer patients and healthy volunteers as a representative sample in order to validate the serum levels." (PMID 24932247, 2014).
breast carcinoma (continued). "In the present study, we evaluated the effect of BPAF on endogenous transcription of TFF1, GREB1 and CTSD in human breast cancer cells." (PMID 24727858, 2014). "It has been shown that Cathepsin D contributes to the multiple disease processes including breast cancer, Alzheimer disease, and HIV." (PMID 24729918, 2014). "In this report, we identified the regulation of MMP1/9 and cathepsin D by c-Myb as a novel mechanism of the matrix-specific breast cancer cell invasion." (PMID 22439866, 2012). "We demonstrated that c-Myb regulates the invasive behavior of breast cancer cells in a matrix-dependent manner, possibly via a novel signaling axis causing the deregulation of MMP1, MMP9, and cathepsin D expression." (PMID 22439866, 2012). "Cathepsin D has been comprehensively studied in breast cancer where overexpression of mRNA and protein has been observed and been shown to be an independent marker of poor prognosis." (PMID 22919486, 2012). "Cathepsin D is another enzyme involved in cell invasion and metastasis, particularly in breast cancer." (PMID 22439866, 2012). "Cathepsin D, an independent marker of poor prognosis in breast cancer that correlates with the incidence of clinical metastasis, was downregulated." (PMID 22691413, 2012). "In this report, we identified the regulation of MMP1/9 and cathepsin D by c-Myb as a novel mechanism of breast cancer cell invasion that is dependent on extracellular matrix composition." (PMID 22439866, 2012). "The effects of siRNA-mediated silencing of cathepsin D in MDA-MB-231MYBup cells described in our study provide further support to the studies documenting the regulatory function of cathepsin D in breast cancer cell migration and invasiveness." (PMID 22439866, 2012). "The aspartic protease cathepsin D (cath-D), a marker of poor prognosis in breast cancer, is overexpressed and secreted at high levels by human epithelial breast cancer cells." (PMID 21311773, 2011). "Cathepsin D is an independent marker of poor prognosis in breast cancer correlated with the incidence of clinical metastasis, and downregulation of Cathepsin D inhibits tumor growth and experimental metastasis of human breast cancer cells." (PMID 21966391, 2011). "The aspartic protease cathepsin-D (cath-D) is overexpressed by human epithelial breast cancer cells and is closely correlated with poor prognosis in breast cancer." (PMID 21311773, 2011). "Previous studies from our laboratory demonstrated that decreased expression of NM23-H1 in MCF-7 breast cancer cells enhances expression of Cathepsin D and Bcl2, which are involved in limiting apoptosis, promoting cell migration and increasing angiogenesis." (PMID 20064251, 2010). "Among these proteins, 15 proteins, including cathepsin D and osteopontin, have been previously reported to be potential markers for breast cancer in serum or tumor tissues." (PMID 18796163, 2008). "Several studies have demonstrated that Cathepsin D is an important prognostic factor in breast cancer, especially in LN- patients." (PMID 17092354, 2006). "Oestrogen and anti-oestrogen regulate pS2 and cathepsin D expression in 3366 tumours as in the human breast cancer cell line MCF-7." (PMID 10839300, 2000). "Cytosolic determinations of cathepsin-D (cath-D), urokinase plasminogen activator (uPA) and its specific inhibitor PAI-1 have shown an association with adverse prognosis in breast cancer." (PMID 10389993, 1999). "Many studies have addressed the clinical value of pS2 as a marker of hormone responsiveness and of cathepsin D (Cath D) as a prognostic factor in breast cancer." (PMID 10070889, 1999).
breast carcinoma (continued). "Our study supports the prognostic impact of immunohistochemically detected cathepsin D expression in the epithelial component of breast cancer." (PMID 9683294, 1998). "Breast cancers with an increased level of cathepsin D in tumour tissue extract have been found to have poor prognosis, but studies performed with immunohistochemistry have produced variable results." (PMID 7819033, 1995). "Commercially available immunoradiometric assays were used for pS2 and total cathepsin D determination in the cytosol fraction obtained from 266 primary breast cancers." (PMID 8123486, 1994). "Determination of its cleavage specificity by SDS-PAGE and amino acid sequence analysis revealed that it was identical to that of cathepsin D, an aspartyl proteinase suggested to be involved in breast cancer development." (PMID 8494701, 1993). "The expression and function of cathepsin D vary among different subtypes of breast cancer." (PMID 39944834, 2025). "Furthermore, our study found that Cathepsin D expression is a powerful and independent prognostic factor for both breast cancer-specific survival (BCSS) and disease-free interval (DFI)." (PMID 38578521, 2024). "Additionally, Cathepsin D has been found to be upregulated and secreted by breast cancer cells, promoting tumor invasion and metastasis by degrading the extracellular matrix and basement membrane in an acidic environment." (PMID 38887235, 2024). "Furthermore, reports showed that kaempferol elicited in vitro and in vivo anticancer activity against breast cancer by down-regulating the expression of cyclin D1, cyclin E, cathepsin D, pIRS-1, pAkt, and pMEK1/2, while up-regulating p21 and Bax expression." (PMID 39478959, 2024). "Cathepsin D expression was positive in 71.2% (679/954) of breast cancer tumours." (PMID 38578521, 2024). "MCF-7 breast cancer cells showed overexpression of cathepsin D in response to zinc exposure." (PMID 38249992, 2024). "The role of Cathepsin D in breast cancer was first reported in a study as early as 1980." (PMID 39080685, 2024). "Expression of Cathepsin D was assessed by immunohistochemical staining of tissue microarrays, in a large well-characterized series of early-stage operable breast cancer (n = 954) from Nottingham Primary Breast Carcinoma Series between the period of 1988 and 1998 who underwent primary surgery." (PMID 38578521, 2024). "CTSD is also considered to be a target in antibody-based therapy for the treatment of triple-negative breast cancer due to its correlation with poor prognosis of breast cancer and providing a tumor-specific extracellular target." (PMID 35976950, 2022). "In human breast cancer, cathepsin D (CTSD), IL4 receptor (IL4R), mucin-1 (MUC1, CD227), and serine protease 3 (PRSS3) may serve as valuable biomarkers for the diagnosis and treatment of breast cancer." (PMID 35787690, 2022). "The cathepsin D in saliva has also been used to diagnose and monitor patients with breast cancer." (PMID 35097122, 2022). "Cathepsin D is also overexpressed in breast cancer and predicts a poor prognosis." (PMID 36009568, 2022). "Since cathepsin D can mediate protease lectures and promote breast cancer invasion and metastasis, the concentration of cathepsin D in the cell membrane can be used to determine the metastasis of breast cancer." (PMID 36381072, 2022). "There is evidence that autophagy modulators chloroquine, KU-55933, and rapamycin from Streptomyces hygroscopicus combined with a recombinant analog of human milk protein lactaptin decreased cathepsin D activity with cytotoxic effects in MDA-MB-231 cell line (breast carcinoma)." (PMID 34198733, 2021). "It has been reported that plasma pro-cathepsin D levels were elevated in breast cancer patients." (PMID 33445607, 2021). "Elevated serum levels of cathepsin D were reported in breast cancer patients and cathepsin D detected in tissues could have diagnostic value for ovarian cancer." (PMID 33802262, 2021).
breast carcinoma (continued). "Recent studies have indicated that CTSD is involved in breast cancer invasion, and inducing CTSD may facilitate breast and gastric cancer cell migration." (PMID 32331211, 2020). "This is consistent with our finding that the ER-rich MCF-7 cells showed more proliferation than the ZR-75-1 cells, suggesting that cathepsin D may control ER-independent progression of breast cancer." (PMID 32846884, 2020). "In summary, deletion of CTSD in myeloid cells did not delay breast cancer progression, while CTSD deficiency in the mammary epithelium strongly impaired tumor development without affecting gross mammary gland function." (PMID 33046706, 2020). "In human breast cancer, CTSD was suggested as a tumor marker long time ago17." (PMID 33046706, 2020). "The expression level of cathepsin D could be a crucial marker in making treatment decisions upon patients with ambiguous luminal A or B breast cancer consequently." (PMID 32846884, 2020). "Cathepsin D has been shown to be over expressed and hyper-secreted in a number of cancers including breast, ovarian, lung, prostate and malignant glioma cancers, and known as a marker for poor prognosis in breast cancer patients." (PMID 32645977, 2020). "Fourth, considering that preclinical studies have also shown pro-cathepsin D overexpression in breast cancer and hepatocellular carcinoma, it was postulated that pleural pro-cathepsin D may serve as a potential biomarker for diagnosing MPE." (PMID 32867726, 2020). "Therefore, we particularly focused on the functional roles of cathepsin D involved in the progression of different breast cancer subtypes." (PMID 32846884, 2020). "According to previous investigations, the role of cathepsin D in breast carcinoma is significant." (PMID 32846884, 2020). "However, in contrast to the CTSD-deficient postmitotic neurons affected in CLN10, breast cancer cells appear to be able to rewire proliferative and survival signaling, e.g., by CREB activation, thereby resuming malignant growth and metastasis." (PMID 33046706, 2020). "By using a conditional CTSD knockout mouse crossed to the transgenic MMTV-PyMT breast cancer model we demonstrate that CTSD deficiency in the mammary epithelium, but not in myeloid cells, blocked tumor development in a cell-autonomous manner." (PMID 33046706, 2020). "In this study, we detected three mitochondrial proteins (CPS1, ATAD3A/ATAD3B, and ABHD11) and one lysosomal protein (cathepsin D) with different expressions in paclitaxel-resistant MCF7/PacR breast cancer cells compared to paclitaxel-sensitive MCF7 breast cancer cells." (PMID 31248089, 2019). "LPMSNs and organosilica NPs seem good candidates for the delivery of pepstatin A (C34H63N5O9), a small hydrophobic pentapeptide which is the most potent inhibitor of cathepsin D, a lysosomal aspartic endopeptidase overexpressed in solid tumors and breast cancer." (PMID 30658511, 2019). "Cathepsin D is a protease involved in the metastasis and angiogenesis of mammary carcinomas." (PMID 30669448, 2019). "Immunohistochemical analysis revealed that the breast cancer cell markers cathepsin D and MMP1 (matrix metalloproteinase 1) were highly expressed in the cocultured bone, indicating that our ex vivo metastasis model mimics the biological events triggered by cancer invasion." (PMID 30400633, 2018). "In addition, different factors like angiogenesis and cathepsin D can be used in the prognostic, predictive, and pharmacodynamics of breast cancer." (PMID 29978332, 2018). "Cathepsin D can be used as predictive factor for breast cancer." (PMID 29978332, 2018). "Furthermore, cathepsin D and peroxiredoxin-5 have been found to be upregulated in breast cancer cell lines in response to radiation therapy." (PMID 29068423, 2017). "KYNU, CTSD and PMP22 are known to be up‐regulated in advanced metastatic cancers and correlate with poor prognosis whereas LAMB1 encodes a laminin‐1 protein shown to have reduced expression in breast cancer." (PMID 25241147, 2015).